IL6 (interleukin 6)
Diseases named in the same sentence as IL6 in open-access papers (continued):
Sharing a sentence is not in itself a finding about the gene and the disease.
Sepsis (continued). "sTREM-1 was able to predict the development of severe sepsis, however, PCT was superior to sTREM-1, CRP and IL-6 in predicting severe sepsis and septic shock on the third day of treatment." (PMID 29282483, 2018). "The inhibition of NF-κB activation in drug-treated animals provides an explanation for the reduced serum levels of TNF-α and IL-6 and the improvement in the sepsis-induced insulin resistance process." (PMID 29760586, 2018). "This study’s novel longitudinal comparison of systemic cytokines in the two separate models demonstrated that the addition of sepsis crosses predictive threshold of IL-6, IL-10, and TNF for immune dysregulation." (PMID 29849508, 2018). "Based on our findings, HBP plays an important role in the initial inflammatory reaction associated with sepsis-induced AKI, presumably by activating M1 macrophages and suppressing TNF-α and IL-6 secretion." (PMID 29723248, 2018). "On the other hand, in CLP-induced sepsis model in HSP70.1/3 knockout mice NF-κB binding/activation, TNFα and IL-6 in lung tissue as well as mortality were increased after sepsis." (PMID 29728738, 2018). "Compared to SECaureus, the production of pro-sepsis cytokine IL-6 is significantly higher with SECepi-activated lymphocytes." (PMID 29584685, 2018). "TNFα and IL-6 are recognized early players in the clinical response to sepsis and shown to be locally produced by intrinsic kidney cells in the early phase of injury." (PMID 30343340, 2018). "In this kinetic experiment, we measured serum levels of proinflammatory cytokines (TNF-alpha, IL-6) that are highly elevated in sepsis." (PMID 30525057, 2018). "A similar pattern of decreased TNFα, IL-6, IFNγ, and IL-10 was also observed in a post-mortem study of stimulated splenocytes from patients who died of sepsis." (PMID 30555806, 2018). "Our findings suggest that MCP-1, sCD14, IL-6, IL-10, cortisol, and HBP are modulated by the source of sepsis and that elevated MCP-1 and cortisol plasma levels are associated with sepsis-induced organ dysfunction." (PMID 29769838, 2018). "Ten hours after sepsis induction, vehicle-treated pups demonstrated a significant increase in serum levels of IL-6 and IL-1β compared to sham pups (55.9 ± 4.2 vs. 0.1 ± 0.1 ng/ml and 377.2 ± 42.6 vs. 4.6 ± 2.6 pg/ml, respectively)." (PMID 29720984, 2018). "AOSD, RHS, and sepsis share pathophysiological aspects, including the prominent role of pro-inflammatory cytokines IL-1, IL-6, and IL-18." (PMID 29642928, 2018). "Similar to adults, it has been suggested that IL-6 concentrations are a strong indicator of sepsis prognosis in neonates." (PMID 30555806, 2018). "The knockdown of Beclin1 has been shown to attenuate HMGB1-mediated release of TNF-α and IL-6 in lethal sepsis via inhibiting NF-kB18." (PMID 30478280, 2018). "In relation to the systemic profile, a significant increase was observed in the levels of TNF, IL-6, and IL-10 in animals of the sepsis group compared to the control (respectively)." (PMID 30524657, 2018). "Our findings of elevated TNFα and IL-6 levels in sepsis-induced AKI are consistent with these reports." (PMID 30343340, 2018). "The secretion levels of two major sepsis-related cytokines IL-6 and TNFα were measured by ELISA and showed a marked decrease in the sera of cKO mice compared with the WT mice." (PMID 29352108, 2018). "We found that IL-6, IL-8, MCP-1 and IL-10 formed a cytokine network in the acute phase of sepsis and that the combined score of IL-6 + IL-8 + IL-10 + MCP-1 correlated with patient prognosis and disease severity." (PMID 30228372, 2018). "Pathological overproduction of IL-6 is found in patients with sepsis and correlates with disease mortality." (PMID 30374077, 2018). "At T24, the concentrations of IL-6 and the reduction in IL-6 level were predictors of survival in patients with sepsis and septic shock." (PMID 30400775, 2018).
Sepsis (continued). "For the first time, we demonstrated that PCT, sTREM-1, CRP and IL-6 were predictors of severe sepsis on the third day of SI; the PCT level had the highest AUC (0.744), with a sensitivity of 79% and a specificity of 63% at a cut-off value of 1.7 ng/ml." (PMID 29282483, 2018). "Our data show association between serum levels of the cytokines IL-4, IL-6, IL-10 and TNF, and cognitive performance of patients with severe sepsis or septic shock." (PMID 29540719, 2018). "Evaluation of these IL-6 boosted mice should be noteworthy as IL-6 is one of the critical cytokines in the development of sepsis." (PMID 30245803, 2018). "Tumor necrosis factor-α and IL-6 are secreted as initial proinflammatory cytokines in sepsis, stimulating the production of thrombopoietin." (PMID 29381746, 2018). "NF-κB signaling is involved in regulating the transcription of sepsis related immunomodulatory mediators associated with the onset of sepsis-triggering organ failure such as TNF-α, IL-6 and iNOS34." (PMID 30297806, 2018). "CQ1-1: can we use procalcitonin (PCT), presepsin (P-SEP,sCD14-ST), and interleukin-6 (IL-6) for the diagnosis of sepsis?" (PMID 29435330, 2018). "In this follow-up cohort study, we advanced our previous work by following-up and comparing the plasma levels of DcR3, PCT, CRP, and IL-6 in 134 sepsis patients from the time when sepsis was suspected to 5–7 days after a pathogen-positive blood culture." (PMID 29541387, 2018). "Preclinical studies favor sepsis as the major driver of the inflammatory response, and clinical studies have shown IL-6 elevation has been tied to sepsis in trauma." (PMID 29849508, 2018). "Inflammatory cytokines, including tumour necrosis factor (TNF)-α, interleukin (IL)-1α, IL-1β, and IL-6, promote the development of sepsis-induced cardiomyopathy." (PMID 29693453, 2018). "The lipoxin A4 agonist, BML-111, alters the expression of TLR2 and 4 in a murine cecal ligation/puncture model of sepsis with improvements in pro-inflammatory IL-6 and TNF-α production." (PMID 29515999, 2018). "In a mouse sepsis model, IL-6 inhibition reduced the expression of tissue C5aR, but to the best of our knowledge the effects of IL-6 inhibition on the anaphylatoxin receptor expression in human CAD have not been investigated." (PMID 30258440, 2018). "Serum TNF-alpha was only detectable in the G-CSF group 12 h after septic insult, whereas various levels of IL-6 were measured throughout the course of sepsis." (PMID 30525057, 2018). "Treatment with KRN shortly after sepsis induction resulted in a worsening of systemic inflammation, with a further elevation in IL-6 levels (58 ± 5 ng/ml) and a significant increase in IL-1β levels (439 ± 27 pg/ml)." (PMID 29720984, 2018). "During sepsis, the levels of IFNγ, IL-6, IL-10, and IL-4 were significantly elevated in the moderate preterm group only." (PMID 30555806, 2018). "Inflammatory cytokines TNFα and IL6, determined from the renal venous blood, were elevated in sepsis." (PMID 30343340, 2018). "In particular, IL-6 an important mediator during the acute response to sepsis that positively correlates with mortality and severity scores in septic patients, was significantly suppressed in HIF-1DF/LysM mice." (PMID 30524296, 2018). "Regulators of thrombopoiesis, such as thrombopoietin, tumor necrosis factor-α, and interleukin (IL)-6, all increase in patients with sepsis and correlate with sepsis severity." (PMID 29381746, 2018). "Sepsis induces upregulation of multiple proinflammatory genes in the diaphragm, including various proinflammatory cytokines such as TNF-α, IL-1β and IL-6 and there is evidence that these cytokines are involved in sepsis-induced diaphragmatic dysfunction." (PMID 30067847, 2018). "We aimed to investigate if reductions in the plasma concentrations of TNF-α, interleukin (IL)-6 and IL-10, and of the IL-6 rate of change at 24 h after ICU admission were survival predictors for Vietnamese patients with sepsis and septic shock." (PMID 30400775, 2018).
Sepsis (continued). "Growing evidence indicates that genetic polymorphisms in genes encoding inflammation-related cytokines, including IL-6, IL-10 and TNF-α, play significant roles in the pathogenesis of sepsis and even contribute to sepsis susceptibility and progression." (PMID 30268141, 2018). "In the cecal ligation and puncture sepsis model, survival rates were improved by sgp130-Fc, which inhibits IL-6 trans-signaling, suggesting the importance of IL-6 trans-signaling inhibition in the systemic inflammatory response." (PMID 30423923, 2018). "Increased IL-6 levels in plasma have been identified in severe forms of sepsis, and correlate with an increased prevalence of mortality." (PMID 30400775, 2018). "A good example is IL-6, the blood levels of which should correlate with the severity and bacterial etiology of sepsis." (PMID 29769838, 2018). "Significant reductions in the levels of circulating interleukin-6 (P = 0.046) and tumor necrosis factor-α (P = 0.008) were found in the sepsis group." (PMID 30666251, 2018). "Our findings indicate that a reduction in IL-6 level of ≥86% at 24 h from ICU admission was a survival predictor for sepsis and septic shock patients comparing with patients who had an increasing IL-6 rate of change." (PMID 30400775, 2018). "In a model of polymicrobial sepsis in DREAM-deficient mice, decreased IL-6, MCP-1, and ICAM-1 release was found in bronchoalveolar lavage fluid." (PMID 29682558, 2018). "HBP plays an important role in the initial inflammatory reaction associated with sepsis-induced AKI, presumably by activating M1 macrophages and suppressing TNF-α and IL-6 secretion." (PMID 29723248, 2018). "For example, in human sepsis, haemoglobin concentrations decrease in a hepcidin-dependent manner during admission, hepcidin and IL-6 concentrations are positively correlated and hepcidin concentrations are highest in those with the most severe disease." (PMID 30046137, 2018). "after inducing sepsis by more than 40% (42% in IL-6, 48% in TNF, and 43% in IL-1β levels) (frames (a)-(c))." (PMID 30364002, 2018). "Raised IL-6 on postoperative day 1 predicts postoperative sepsis in patients undergoing major gastrointestinal surgery." (PMID 29849595, 2018). "TNF-α, interleukin-1β (IL-1β), IL-6, and monocyte chemotactic protein-1 (MCP-1) are hallmark inflammatory mediators of sepsis that constitute the cytokine storm." (PMID 29980671, 2018). "Improve the Neutrophil function.Increase the phosphorylation of p38 MAP kinase.Control sepsis-induced organ damageSupresses IL-6 and MCP-1 level.Control the bacteraemia." (PMID 30534129, 2018). "IL-6 inhibition is previously shown to attenuate expression of anaphylatoxin receptors in an experimental model of sepsis." (PMID 30258440, 2018). "The decrease in IL-6 levels measured in the groups receiving tadalafil compared to the untreated sepsis group also corroborates this." (PMID 27622284, 2017). "Other studies have suggested that IL-6, in association with IL-1β, is implicated in the NOS-dependent systemic vasodilatation seen during sepsis." (PMID 28424078, 2017). "In the previous study, the levels of TNF-α and IL-6 in the plasma were also substantially increased in CLP-induced sepsis." (PMID 28694565, 2017). "During sepsis, inflammatory cytokines in particular IL-6 and TNFα induce a state of insulin resistance." (PMID 28233125, 2017). "Because phagocytic cells are the major source of inflammatory mediators, such as tumor necrosis factor-α (TNF-α), interleukin (IL)-1β, IL-6 and matrix metalloproteinases (MMPs), involved in the pathogenesis of sepsis." (PMID 28661460, 2017). "IL-6 was elevated to a lesser extent, with a median level in these HLH patients of 51.1 pg/mL, though among HLH patients with sepsis, as expected, a higher median IL-6 level was detected (244.6 pg/mL)." (PMID 28487810, 2017). "Increased levels of TNFα, IL-1, and IL-6 have been reported to occur more often in sepsis than SIRS." (PMID 29459855, 2017).
Sepsis (continued). "Sepsis-related hepatic dysfunction is associated with elevated plasma levels of endothelin-1, TNF-α and IL-6." (PMID 28542386, 2017). "Considering the key role of IL-6 in mediating the acute phase response, its value as a prognostic biomarker in sepsis and various acute organ injuries has been extensively investigated in clinical and experimental studies." (PMID 28424078, 2017). "In conclusion, 5-HT increased serum cytokine secretion, such as TNF-α and IL-6, and aggravated the mortality of sepsis by an excessive inflammatory response." (PMID 28694565, 2017). "Future studies are needed to reconcile the discrepancy between the commonly recognized merits of using IL-6 concentrations as a detrimental prognostic factor in sepsis in a clinical setting and its protective role in experimental sepsis and ARDS." (PMID 28424078, 2017). "Serum hs-CRP levels have been reported to positively correlate with serum IL-6, which is always increased in acutely ill patients with severe sepsis." (PMID 29221433, 2017). "Before, and at 12, 18 and 22 h of progressive sepsis, systemic and renal hemodynamics, cortex microcirculation and plasma IL-6 and TNF-α were measured." (PMID 28569136, 2017). "Plasma IL-6 levels increased during untreated sepsis and decreased during the resuscitation period in both groups, but they were lower at the end of the study in the Lac ≥10% group than in the Lac <10% group (p = 0.047)." (PMID 28499395, 2017). "Among the three sepsis subgroups, the plasma concentrations of TNF-α, IL-6 and IL-1β in the severe sepsis/septic shock subgroups were significantly higher compared with the mild sepsis subgroup." (PMID 28472164, 2017). "Increased levels of activated γδ T-cells are seen in the circulation of patients with trauma and sepsis, and blockade of IL-6 activity has been shown to improve the outcome." (PMID 28368347, 2017). "The plasma concentrations of TNF-α, IL-6 and IL-1β were significantly higher in the sepsis patients compared to the healthy volunteers (P < 0.0001), and that they increased with the aggravation of sepsis (P < 0.05)." (PMID 28839236, 2017). "In an LPS-induced shock mouse, which is considered to be a model of sepsis, serum cytokines such as IL-6 and TNF-α were increased, and these cytokines induced organ injury and mortality." (PMID 28800777, 2017). "We have also reported on the time course of cytokines in sheep sepsis study, in which IL-6 and PARP activation in lung tissue peaked at 8 hours and 12 hours after injury." (PMID 28982177, 2017). "Cumulatively, the sepsis-induced proinflammatory response, with the notable exception of IL-6, is suppressed by NTM, contributing to maintaining homeostatic regulation." (PMID 28628637, 2017). "Sepsis was associated with increased TNF-α and IL-10 levels in the hypothalamus and higher IL-1β, IL-6, and IL-10 in the brainstem." (PMID 27229490, 2017). "Although interleukin-6 (IL-6) is a good prognostic marker for sepsis, the relationship between mitochondrial dysfunction and IL-6 remains poorly understood." (PMID 28549777, 2017). "Consistent with previous studies, IL-6 was significantly upregulated in the plasma samples from sepsis patients, as well as in the BAL fluid samples, while minimal and insignificant detection of IL-2 and IL-4 was observed." (PMID 28287491, 2017). "A sepsis-like inflammatory response to LPS was confirmed by the expression of classical cytokines such as TNFα and IL-6." (PMID 28276491, 2017). "Using SOFA and APACHE II as accepted scores of the severity of sepsis, a significant correlation has been demonstrated between these scores and serum levels of some analyzed biomarkers, such as sTREM-1, IL-6, and PCT." (PMID 28380034, 2017). "We found that plasma concentrations of TNF-α, IL-1β and IL-6 in the sepsis group were significantly higher than in the healthy control group, and the levels of these cytokines also increased with sepsis severity." (PMID 28472164, 2017).
Sepsis (continued). "Interleukin-6 (IL-6) is also an acute phase protein involved in inflammatory processes, including septicemia and the inflammatory response syndrome (SIRS), but has never been studied in dogs with HWD." (PMID 29143684, 2017). "The shared variance of IL-8, IL-6, and IL-10 (factor 2 in factor analysis) was correlated with the development of sepsis." (PMID 28769538, 2017). "al suggested that IL-6 blockade down-regulated C5aR receptor expression and significantly improved survival in a rodent model of sepsis." (PMID 28832655, 2017). "Nevertheless, IL-6 was shown useful for sepsis diagnostics in neonatal/pediatric critically ill patients." (PMID 29063386, 2017). "Sensitivity and specificity of modifications in percentage of interleukin 6 or Procalcitonin in relation to survival in function of different cutoff points in patients with severe sepsis/septic shock." (PMID 28380034, 2017). "TNF-α is the primary inflammatory mediator in sepsis as it regulates other downstream cytokines such as IL-6 and IL-10." (PMID 28086962, 2017). "High expression of IL-10 and TNF-α correlate with poor prognostic in patients with severe sepsis whereas higher levels of TNF-α, IL-6, and soluble TNF receptor (sTNFR) are associated with early hemodynamic deterioration." (PMID 29269852, 2017). "In the early response of sepsis, both IL-6 and TNF-α are major pro-inflammatory cytokines and are involved in physiological dysfunction." (PMID 28661460, 2017). "The use of filgrastim caused minor changes in the areas under the ROC curves of IL-8 (0.88; P = 0.04) and IL-6 (0.78; P = 0.037) for sepsis discrimination." (PMID 28769538, 2017). "Pro-inflammatory cytokines such as TNF-α, IL-1ß, and IL-6 play a more important role in the pathogenesis of sepsis and septic shock." (PMID 28320333, 2017). "Levels of the inflammatory parameter IL-6 decreased significantly in the sepsis groups receiving tadalafil in comparison with the untreated sepsis group (p<0.05)." (PMID 27622284, 2017). "Since the pathogenic mechanism of sepsis involves intravascular inflammation mediated by various proinflammatory cytokines, we measured the serum levels of TNF-α and IL-6 in BALB/c mice." (PMID 27937124, 2017). "PTX-3 levels valuably discriminated the presence of at least sepsis on each day (minimal AUC = 0.82) as well as of septic shock (minimal AUC = 0.73) and was overall comparable to IL-6 and PCT." (PMID 28793880, 2017). "Induction of sepsis by CLP resulted in early 1.5–20-fold increases in IL-6, IL-10, IFNγ and TNFα over that induced by sham surgery." (PMID 28724977, 2017). "IL-6 levels tend to remain high in sepsis, and one of its biological effects is the induction of fever." (PMID 28769538, 2017). "Having found that p32 is involved in the LPS-induced sepsis model, we measured serum IL-6 after intraperitoneally injecting LPS." (PMID 28549777, 2017). "Muller and colleagues conducted a study in consecutive critically ill patients to compare the usefulness of serum concentration of calcitonin precursor, CRP, IL-6 and lactate for the diagnosis of sepsis." (PMID 28794881, 2017). "Our study is the first to demonstrate that GIK decreased the rate of mortality in a rat model of sepsis, decreased the production of intestinal tissue proinflammatory cytokines, including IL-1β, IL-6 and TNF-α, and increased the level of IL-10." (PMID 28428961, 2017). "Interleukin-1β (IL-1β), IL-6, IL-10 and tumor necrosis factor-α (TNF-α) are some of the classical sepsis-associated cytokines." (PMID 28176831, 2017). "The usefulness of sepsis biomarkers, such as procalcitonin (PCT) and presepsin (PSEP), has been reported; PCT and PSEP have been reported to be superior to C-reactive protein (CRP) and interleukin-6 for sepsis diagnosis and assessment of sepsis severity." (PMID 28702197, 2017). "PTX-3 reveals diagnostic value for sepsis and septic shock during the first week of intensive care treatment, comparable to interleukin-6 according to latest Sepsis-3 definitions." (PMID 28793880, 2017).